ZNF107 (zinc finger protein 107)
Description:
May be involved in transcriptional regulation.
Synonyms: ZFD25; ZNF588; smap-7; Y8
Tractability: PROTAC: UniProt records ubiquitination sites on it; ubiquitination databases record sites on it.
Gene: Protein-coding gene on chromosome 7 (64,666,099 to 64,711,577, forward strand). Ensembl gene ENSG00000196247.
Subcellular location: Nucleus
Gene Ontology:
Molecular function: protein binding; transcription cis-regulatory region binding
Biological process: regulation of transcription by RNA polymerase II; negative regulation of transcription by RNA polymerase II
Cellular component: nucleus
Genetic constraint (gnomAD): Loss-of-function variants: 13 observed, 8.53 expected, observed/expected ratio (o/e) 1.52, 90% interval 0.96 to 1.93. That is too few expected variants to judge how well the gene tolerates losing a copy. Missense variants: 926 observed, 957.26 expected, observed/expected ratio (o/e) 0.97, 90% interval 0.92 to 1.02. Synonymous variants: 305 observed, 317.88 expected, observed/expected ratio (o/e) 0.96, 90% interval 0.87 to 1.05.
Homologues: Orthologues: chimpanzee ZNF273 (99% identical), macaque ZNF107 (96% identical), chimpanzee ZNF107 (91% identical), zebrafish znf646 (21% identical), zebrafish si:dkey-89b17.4 (21% identical), Drosophila melanogaster zf30C (20% identical), Drosophila melanogaster CG18011 (19% identical), zebrafish znf576.1 (18% identical), Drosophila melanogaster CG6791 (17% identical), Drosophila melanogaster CG30020 (16% identical), Drosophila melanogaster hang (15% identical), Caenorhabditis elegans ztf-15 (14% identical), and 22 more. Paralogues in human: ZNF91 (68% identical), ZNF208 (67% identical), ZNF99 (65% identical), ZNF729 (64% identical), ZNF160 (45% identical), ZNF420 (43% identical), ZNF184 (41% identical), ZNF347 (41% identical), ZNF845 (39% identical), ZNF84 (38% identical), ZNF594 (38% identical), ZNF665 (37% identical), and 24 more.
Diseases named in the same sentence as ZNF107 in open-access papers:
ZNF107 is named in the same sentence as 7 diseases in open-access papers, as found by Europe PMC text mining. Sharing a sentence is not in itself a finding about the gene and the disease. The quoted sentences say what the papers report.
glioma (1 paper, 2017). A benign or malignant brain and spinal cord tumor that arises from glial cells (astrocytes, oligodendrocytes, ependymal cells). "To determine if the repression of HRAS and ZNF107 were sarcoma specific, we looked at their expression in senescent SNB19 glioma cells, senescent A549 and H1975 lung cancer cells and quiescent H358 lung cancer cell lines." (PMID 28855512, 2017).
neurodevelopmental disorder (1 paper, 2022). A behavioral and cognitive disorder with onset during the developmental period that involves impaired or aberrant development of intellectual, motor, or social functions. "Among the unique DMGs, we found several genes linked to neurodevelopmental disorder and ASD, including XK related 6 (XKR6), zinc finger protein 107 (ZNF107), and myeloma-overexpressed gene 2 protein (MYEOV2) in the ASD with 16.p11.2 del." (PMID 35978033, 2022).
tumor (1 paper, 2022). "According to the expression levels and regression coefficients, the downregulated BAX, PWP2, SERTAD1, S1PR4, ZFAND1, NUDT13 and ZNF107 with HR < 1 were considered as tumor suppressors, whereas the MVD, BAD, CPNE7, CPNE7, UTP23 and ZNF124 upregulated with HR > 1 were regarded as oncogenes." (PMID 36685828, 2022).
ZNF107 also shares sentences with these, for which no sentence is quoted: bacterial infection (1 paper); cancer (1); lung carcinoma (1); sarcoma (1).